ADAM10 (ADAM metallopeptidase domain 10)
Diseases named in the same sentence as ADAM10 in open-access papers (continued):
Sharing a sentence is not in itself a finding about the gene and the disease.
prion disease (continued). "Similarly, ADAM10 activation has been proposed as a potential treatment for prion disease, because ADAM10 sheds the cellular prion protein and conditional deletion of ADAM10 in forebrain neurones reduces survival time in a mouse model of prion disease." (PMID 28620033, 2017). "However, the role of ADAM10 in prion disease is complicated, because ADAM10 also reduces spread of the disease throughout the brain and reduces neuropathological consequences." (PMID 28620033, 2017). "Finally, these findings will also aid the prediction of potential side effects of ADAM10-activating drugs as they are considered for the treatment of AD and prion disease." (PMID 26802628, 2016). "Understanding this dual role of ADAM10 in prion disease brings together current concepts of prion biology and might reveal a mechanistic insight into important pathophysiological processes." (PMID 25654651, 2015). "However, due to the perinatal lethality of these mice, the influence of ADAM10 on the course of prion disease remained unsolved." (PMID 25654651, 2015). "Furthermore, identification of ADAM10 as the sheddase of PrPC opens the avenue to devising novel approaches for therapeutic interventions against prion diseases." (PMID 21619641, 2011). "Therefore, ADAM10-mediated shedding might play a dual role in prion diseases due to currently unknown factors and cofactors." (PMID 37854584, 2023). "In conclusion, the ADAM10-mediated shedding might play a dual role in prion diseases, and whether it is protective or rather disease-supporting might depend on critical molecular stoichiometries, cofactors, and currently unknown cellular modalities as well as species and prion strains." (PMID 35084572, 2023). "Therefore, activation of ADAM10 aiming at increasing normal PrP breakdown and depleting PrPsc could be seen as putative therapeutic strategy for prion disease." (PMID 33413403, 2021). "Interestingly, protective effects of ADAM10 might be hijacked in prion diseases since a reduction of the protease in prion disease has recently been reported in vitro and in vivo." (PMID 25654651, 2015). "In summary, depletion of the PrPC sheddase ADAM10 in neurons of the forebrain led to a significant reduction in incubation times of more than 40 days until onset of terminal prion disease without affecting overall clinical presentation." (PMID 25654651, 2015). "We show that lack of ADAM10 leads to (i) elevated (membrane) levels of PrPC, (ii) drastically shortened incubation times of prion disease, (iii) increased prion conversion, and (iv) upregulation of calpain levels." (PMID 25654651, 2015). "Whereas for striatum we observed neuropathological changes typically found in terminal prion disease irrespective of the ADAM10 status, we found an apparently reduced degree of spongiosis in the cerebellum and brain stem of A10 cKO mice compared with terminally diseased littermate controls." (PMID 25654651, 2015). "However, cell culture models as well as mice with pan-neuronal depletion of ADAM10 did not allow investigation of the role of PrP shedding in prion diseases." (PMID 25654651, 2015). "Apart from prion disease, in other neurodegenerative proteinopathies, where PrPC-PrPSc conversion does not play a role, ADAM10-mediated shedding of PrPC might solely be protective due to reduction of the receptor as well as the production of a soluble blocker of toxic oligomers." (PMID 25654651, 2015). "However, it is not clear whether ADAM10 can also target the PrPSc proteins and what impact this may have on the development of prion diseases." (PMID 25654651, 2015).
amyloid (9 papers, 2010 to 2024). "Overexpression of these mutated forms of human ADAM10 in a mouse model of AD showed an increase in amyloid plaques and reactive gliosis compared to overexpression of wild-type human ADAM10, indicating that the mutated form of ADAM10 has reduced α-secretase activity towards APP." (PMID 37175729, 2023). "Our Western blot and immunohistochemistry results proved that YXQN increased the levels of CTFα and sAPPα by the higher expression of ADAM10, to play a neurotropic function against amyloidosis formation in AD mice." (PMID 28603494, 2017). "In summary, we hypothesized that the improvement of learning and memory deficits and reduction of amyloidosis in APP23/PS45 mice may be related to the regulation of ADAM10 protein expression and enzyme activity by ALA." (PMID 39030577, 2024). "Importantly, a mild increase of only 30% of mature ADAM10 levels in mouse brains was sufficient to lower amyloid β levels and prevented amyloid pathology in an AD mouse model." (PMID 30833305, 2019). "ADAM10, a competitor of BACE1, is not only promoting the expression of α-secretase that combats formation of amyloidosis, but also enhancing release of neuroprotective sAPPα." (PMID 29755351, 2018). "We assessed the amyloidosis changes by YXQN administration, and also detected the proteases involved in the proteolytic process of APP, including ADAM10, BACE1, and PS1, in order to develop the potential Chinese medicine for AD treatment." (PMID 28603494, 2017). "An increase in ADAM10 activity shifts the balance of APP processing toward APPs-alpha and protects the brain from amyloid deposition and disease." (PMID 28367112, 2017). "In AD transgenic models in which ADAM10 is over-expressed, β-secretase mediated processing of APP decreases, amyloid plaque formation is lessened, and the cognitive capacities of the dual transgenic animals is improved." (PMID 20161760, 2010).
cognitive decline (9 papers, 2017 to 2025). "Our prior research highlighted the elevated level of active ADAM10 in the cortex and striatum as a crucial factor in the synaptic dysfunction and cognitive decline associated with HD." (PMID 39112663, 2024). "Collectively, these findings support ADAM10 inhibition as a valid therapeutic strategy to counter cognitive decline in HD." (PMID 39112663, 2024). "Imbalances between BACE1 and ADAM10 protein expression and enzyme activity where BACE1 is higher than ADAM10 may result in increased production and accumulation of Aβ peptides which can progress to cognitive decline and neurodegeneration." (PMID 39711362, 2025). "Conversely, ADAM10 inhibition is neuroprotective and prevents cognitive decline in HD mice." (PMID 39112663, 2024). "In this regard, the evaluation of ADAM10 plasma levels in patients with suspected cognitive decline may allow early interventions that could retard or even prevent the onset of AD." (PMID 33670873, 2021). "Here, we used different models to investigate whether the plasmatic levels of ADAM10 would be efficient to predict cognitive declines in older adults after a 3-year follow-up period." (PMID 33419480, 2021). "We showed that the increase in ADAM10 plasma levels influences the decrease of the MMSE score values in the follow-up, and this seems to be more significant in those with normal MMSE at baseline, therefore proving that ADAM10 plasma levels can be a predictor of cognitive decline." (PMID 33419480, 2021). "Thus, the measurement of ADAM10 in patients with suspected cognitive decline, but who have not yet reached such a decline, may allow early interventions that could retard or even prevent the AD onset." (PMID 33419480, 2021).
Hodgkins lymphoma (9 papers, 2013 to 2025). A heterogeneous group of malignant lymphoid neoplasms of B-cell origin characterized histologically by the presence of Hodgkin and Reed-Sternberg (HRS) cells in the vast majority of cases. "Over-expression of ADAM10 in Hodgkin lymphoma resulted in an increased release of NKG2D ligands (NKG2D-L) and reduced activation of effector T lymphocytes." (PMID 31311583, 2019). "We also demonstrated that in mesenchymal stromal cells (MSC) from Hodgkin lymphoma (HL), ADAM10 binds to specific fluorescent inhibitors targeting its active site, colocalizing with Rab5-positive early endosomes and with LysoTrackerRed in endolysosomal vesicles." (PMID 34067041, 2021).
asthma (8 papers, 2015 to 2022). "In an experimental asthma model, ADAM10 inhibitor administration significantly attenuated airway hyperreactivity, suggesting that increased ADAM10 activity predisposes to allergic disease." (PMID 25933166, 2015). "In an IgE-dependent asthma model, B-cell-specific ADAM10-knockout mice have strikingly reduced signs of allergic inflammation in the lung." (PMID 30013551, 2018). "Although the regulation of IgE expression by CD23 is complex and not fully understood, these data have lead the authors to propose ADAM10 as a therapeutic target for asthma." (PMID 30013551, 2018). "Inhibition of ADAM10 activity could be beneficial for several diseases, in particular cancer, inflammatory diseases, asthma, and skin disorders." (PMID 26668317, 2016). "Furthermore, while clinically relevant features of human asthma including antigen-specific IgE, mucus, and airway resistance were clearly ADAM10 dependent, eosinophil infiltration was strain dependent only." (PMID 25933166, 2015). "Finally, inhibition of ADAM10 shedding of CD23, the low affinity receptor for immunoglobulin E (IgE) on B cells, has been proposed as a potential therapy for asthma, since specific deletion of ADAM10 in B cells is protective against asthma in a mouse model." (PMID 34201472, 2021). "On B-cells, ADAM10 cleavage of the low-affinity IgE receptor CD23 promotes allergy and asthma, cleavage of ICOS ligand impairs antibody responses, and cleavage of the BAFF–APRIL receptor transmembrane activator and CAML interactor, and BAFF receptor, reduce B-cell survival." (PMID 30013551, 2018). "ADAM10 may promote cancer progression by shedding and release of EGF receptor ligands betacellulin and EGF, for example, and may promote asthma by cleaving the low-affinity immunoglobulin E receptor CD23." (PMID 28620033, 2017).
cervical carcinoma (8 papers, 2013 to 2024). A carcinoma arising from either the exocervical squamous epithelium or the endocervical glandular epithelium. "Elevated levels of ADAM10 have been associated with poor survival in cervical cancer." (PMID 39286024, 2024). "Here, we present a comparison of multiple cellular model systems to study novel combinatorial treatments to overcome chemotherapy resistance in cervical cancers focusing on the inhibition of the metalloproteases ADAM10 and ADAM17." (PMID 39286024, 2024). "The inhibition of SNHG20 can reduce ADAM10 protein expression, resulting in decreased cervical cancer cell proliferation." (PMID 37176052, 2023). "For example, lncRNA SNHG20 promoted cell proliferation and invasion via miR-140-5p-ADAM10 axis in cervical cancer." (PMID 32943989, 2020). "SNHG20 is highly expressed in cervical cancer and promotes proliferation and invasion of cervical cancer cells through the miR-140-5p/ADAM10/MEK-ERK axis." (PMID 30744670, 2019). "In cervical cancer, ADAM10 is the target of miR-140-5p, which is controlled by the SNHG20 lncRNA." (PMID 37176052, 2023). "Similarly, SNHG20 enhanced cell proliferation and invasion via the miR‐140/ADAM10 axis in cervical cancer." (PMID 33089952, 2020). "Relatively little constitutive ADAM10 was seen on fibrosarcoma and cervical carcinoma cells." (PMID 24130797, 2013). "We discovered three events in the genes ADAM10, RNPS1, and CLSPN that were previously reported to play a role in the progression or prognosis of cervical cancer." (PMID 37176052, 2023).
COVID-19 (8 papers, 2021 to 2025). A disease caused by infection with severe acute respiratory syndrome coronavirus 2. "Since ADAM10 regulates proteolytic cleavage of several key proteins acting in synapse formation, axon signaling and cell adhesion and regulating intestinal permeability it could aid in activating key pathways that are altered in COVID-19 pathogenesis." (PMID 34753980, 2021). "The ‘prevalent’ ‘candidate genes’ (ADAM10, ADAM17, AKT1, CTNNB1, ESR1, FGFR1, PIK3CA) might have the most prominent pathophysiological relevance in COVID-19." (PMID 36229517, 2022). "Furthermore, considering that TIM3 is cleaved in both ADAM17 and a disintegrin and metalloproteinase domain-containing protein 10 (ADAM10), we measured ADAM10 (transcriptional level), but our data showed that ADAM10 was not increased in any of the COVID-19 patient groups." (PMID 34445140, 2021).
head and neck squamous cell carcinoma (8 papers, 2015 to 2025). A squamous cell carcinoma that arises from any of the following anatomic sites: lip and oral cavity, nasal cavity, paranasal sinuses, pharynx, larynx, and salivary glands. "One study tested whether restoring Notch signaling in ADAM10-deficient mice would block tumor development and showed that the loss of ADAM10 promotes head and neck squamous cell carcinoma (HNSCC) tumorigenesis by impairing Notch signaling." (PMID 36591235, 2022). "The results from The Cancer Genome Atlas revealed highest ADAM‐10 mRNA level in T2 stage of current smokers with head and neck squamous cell carcinoma (HNSCC)." (PMID 36946281, 2023). "On the other hand, it has been shown that the activation of hsa-miR-494-3p exhibits a strong ability to reduce cancer stemness in head and neck squamous cell carcinomas by targeting Bmi1 and ADAM10, which correlates with longer survival time." (PMID 30234021, 2018). "Moreover, LAG3 and ADAM10 expression was assessed to understand the translational relevance of LAG3 shedding in a cohort of patients with head and neck squamous cell carcinoma (HNSCC)." (PMID 30400822, 2018).
non-small cell lung carcinoma (8 papers, 2015 to 2025). A group of at least three distinct histological types of lung cancer, including non-small cell squamous cell carcinoma, adenocarcinoma, and large cell carcinoma. "To assess the prevalence of ADAM10 expression in human non-small cell lung cancer (NSCLC), we utilized combined data from the TCGA and GTEx repositories, as well as TCGA tumor tissue data." (PMID 39991567, 2025). "In future research, we will deeply investigate the regulatory mechanism of ADAM10, such as how its expression is increased in non-small cell lung cancer." (PMID 39991567, 2025). "This study employs both the TCGA database and patient samples to demonstrate that ADAM10 is highly expressed in non-small cell lung cancer (NSCLC) compared with normal tissue at different stages." (PMID 39991567, 2025). "Despite having only a limited number of Chinese samples (n=12 pairs), examination of the TCGA database revealed that ADAM10 expression reached its highest level in Stage III non-small cell lung cancer (NSCLC) patients." (PMID 39991567, 2025). "Recently, Fang and colleagues demonstrated that IDO1 regulates expression of ADAM metallopeptidase domain 10 (ADAM10) via IDO1-Kyn-AhR pathway in non-small cell lung cancer (NSCLC) cells and that the induction of ADAM10 downregulates the NKG2D Ligand (NKG2DL)." (PMID 37876966, 2023). "In human patients with non-small cell lung cancer, ADAM10 overexpression activated the Notch1 signaling pathway, leading to increased cell migration and invasion." (PMID 33535178, 2021). "For instance, miR-449a inhibited cell invasion and migration by targeting ADAM10 in human non-small cell lung carcinoma." (PMID 32256208, 2020). "The expression of ADAM10 is significantly increased in non-small cell lung cancer (NSCLC) tissues, particularly in metastatic tissues." (PMID 25333745, 2015). "Guo groups found that ADAM10 could promote migration and invasion of human non-small cell lung cancer cells via activating Notch1 signaling pathway." (PMID 32256208, 2020). "In non-small cell lung cancer (NSCLC), ADAM10 is overexpressed in malignant tissues and metastatic sites compared to normal tissues." (PMID 40427200, 2025). "In diverse cancers such as human non-small cell lung cancer and oral squamous cell cancer, TRP channels and ADAM10 have been shown to be overexpressed." (PMID 39497138, 2024). "Interestingly, ADAM10 upregulation appears to play an important role in disease progression in various squamous cell cancers, such as oral SCC, tongue SCC, and non-small cell lung cancer." (PMID 38399697, 2024).
liver cancer (7 papers, 2014 to 2026). An epithelial or non-epithelial malignant neoplasm that arises from the liver. "After knocking down ADAM10, the proliferation, invasion, and migration of the HepG2 liver cancer cell line were significantly inhibited." (PMID 39346916, 2024). "The progression from hepatitis B infection to cirrhosis and eventually to liver cancer is a classic tumorigenic process, so we also investigated the expression profiles of ADAM10 in hepatitis B and cirrhosis patients." (PMID 39346916, 2024). "The results showed that liver cancer patients with concomitant HBV infection had higher levels of ADAM10 expression when compared to HBV-negative liver cancer patients." (PMID 39346916, 2024). "ADAM10 also plays an important role in the immune escape of liver cancer." (PMID 40563539, 2025). "In addition to the TCGA dataset, nearly all liver cancer datasets indicate that the transcription levels of ADAM10 in liver cancer tissues were significantly higher than their corresponding adjacent tissues or normal liver tissue samples." (PMID 39346916, 2024). "Furthermore, we also observed that higher ADAM10 expression was often found in liver cancer patients with the following characteristics: age equal to or less than 65 years, larger tumors, G3 and G4 stage patients, higher AFP levels, microsatellite lesions, TACE sensitivity, and sorafenib resistance." (PMID 39346916, 2024). "Our study corroborates these findings, as we identified abnormal overexpression of ADAM9, ADAM10, ADAM15, and ADAM17 in liver cancer tissues through both GEPIA website analysis and PCR experiments." (PMID 39346916, 2024). "The results confirmed that ADAM9, ADAM10, ADAM15, and ADAM17 exhibited an upregulation trend in at least one liver cancer cell line, consistent with our earlier predictions." (PMID 39346916, 2024). "Prior research has documented a noteworthy upregulation of ADAM family members, particularly ADAM9, ADAM10, and ADAM17, in liver cancer, indicating a close link with tumor advancement." (PMID 39346916, 2024). "In addition to the ADAM10 gene, ADAM9 and ADAM17 are the other frequently reported genes in liver cancer, playing a crucial regulatory role in chemotherapy resistance and malignant tumor progression." (PMID 39346916, 2024). "However, the presence of cirrhosis in liver cancer patients had no impact on the expression of ADAM10." (PMID 39346916, 2024). "ADAM10 was upregulated in primary liver cancer when compared to normal liver tissue." (PMID 24952873, 2014).